IL6 (interleukin 6)
Diseases named in the same sentence as IL6 in open-access papers (continued):
Sharing a sentence is not in itself a finding about the gene and the disease.
iron deficiency (108 papers, 2008 to 2026). "Findings indicate that chronic inflammation drives functional iron deficiency through IL-6-hepcidin-mediated sequestration of iron, resulting in reduced bioavailability and altered mitochondrial activity in immune and epithelial cells." (PMID 41827911, 2026). "Hepcidin synthesis is stimulated by IL-6, particularly under low-carbohydrate or energy-restricted conditions, while iron deficiency itself can limit TPO activity and T4 to T3 conversion." (PMID 41515177, 2025). "Thirdly, IL-6 production can also stimulate hepcidin hormone production, inhibiting iron absorption in the intestine or macrophages, potentially leading to iron deficiency anaemia." (PMID 40077727, 2025). "In neonatal mammals, inflammatory signals such as IFN-γ and IL-6 can inhibit differentiation of erythroid progenitor cells, disrupt iron recycling, and sequester iron within macrophages, leading to functional iron deficiency." (PMID 41306959, 2025). "In patients with inflammation-associated iron deficiency, the release of cytokines such as interleukin-6 and thrombopoietin further stimulate platelet production." (PMID 41463898, 2025). "Searches have examined the pathophysiological processes of iron deficiency in inflammatory conditions, showing that it is triggered by pro‐inflammatory cytokines (IL‐6, IL‐1, TNF‐α)." (PMID 40637365, 2025). "LF also shows potential in the treatment of cancer anemia—by regulating levels of hepcidin and IL-6, it restores normal iron transport, minimizing the risk of both iron deficiency and iron over-accumulation, which can promote cancer development." (PMID 40286136, 2025). "Increased hepcidin—induced by pro-inflammatory cytokines such as IL-6—leads to iron sequestration in macrophages and the liver, resulting in functional iron deficiency even in the presence of adequate iron stores." (PMID 41440517, 2025). "Dietary iron restriction inhibits the pro-inflammatory response of peritoneal cells to M. leprae in vitro - In our study, iron deficiency resulted in lower secretion of IL-6 and TNF by peritoneal cells infected in vitro with M. leprae." (PMID 39166620, 2024). "Open heart surgery in itself provokes elevated interleukin 6, which in turn causes transferrin deficiency, leading to absolute or functional iron deficiency." (PMID 39590219, 2024). "Bone marrow involvement, tumor-associated blood loss, and iron deficiency due to overexpression of cytokines such as IL-6 have been shown to cause the occurrence of chronic anemia in cancer patients." (PMID 38339324, 2024). "It is presumed that a deficiency in hepcidin due to iron deficiency, increasing IL6, promotes mucosal immune function by acting directly on epithelial cells, including goblet cells." (PMID 39341502, 2024). "Given the suggested association between serum IL-6 levels and metabolic abnormalities at the tumor site, we investigated the correlation between metabolic and nutritional disorders and the inflammatory response in individuals." (PMID 38510850, 2024). "The high platelet count is likely due to increased thrombopoiesis, which is induced by higher plasma levels of thrombopoietin and IL-6 or is caused by iron deficiency." (PMID 36984554, 2023). "Lastly, magnesium deficiency has been associated with the increased expression of interleukin-6 and the initiation of an inflammatory response." (PMID 37836583, 2023). "Magnesium deficiency has been linked with the upregulation of interleukin-6, inhibiting endothelial proliferation and thereby contributing to the formation of atherosclerotic plaques and the activation of the coagulation cascade." (PMID 37836583, 2023). "For example, intracellular iron deficiency induced by either iron chelation or overexpression of ferroportin, the only known iron exporter, attenuated LPS-stimulated TNFα and IL-6 production in peritoneal macrophages." (PMID 35956279, 2022).
iron deficiency (continued). "In CKD, patients with functional iron deficiency have higher hepcidin levels, which are predicted by the degree of inflammation (e.g., levels of ferritin, fibrinogen, IL-6)." (PMID 35334593, 2022). "A retrospective cohort study found that high IL-6 levels in more than 50% of the patients were associated with clinical outcomes such as iron deficiency, decreased left ventricular ejection fraction, and NOAF." (PMID 35892443, 2022). "Baseline iron deficiency was associated with greater increase in IL-6 levels (mean difference in change: 0.52 ng/L, 95%CI 0.03–1.00, P = .04) over 3 years." (PMID 34533774, 2022). "Magnesium deficiency in a rat model of endotoxin shock also promoted the secretion of proinflammatory cytokines, including interleukin-6, tumor necrosis factor-alpha, and interleukin-1-beta, which intensify the failure of various organs." (PMID 36424547, 2022). "In conclusion, treating iron deficiency by targeting hepcidin or IL-6 signaling or rebalancing the BMP-/TGF-β-dependent pathways represents innovative strategies that need to be addressed as complements to conventional therapies in robust clinical trials." (PMID 33672218, 2021). "The current study has shown the importance of considering the levels of IL-6 and hepcidin along with iron profiles in older patients with chronic diseases to distinguish the difference between true iron deficiency and functional iron deficiency." (PMID 32095285, 2020). "The iron deficiency and the pro-inflammatory cytokines/inflammation (IL-6, IL-1β and TNFα) act as positive regulators." (PMID 31172340, 2019). "Iron deficiency in acutely ill hospitalized children (n = 142, mean age = 3 years), in Malawi, has been linked with increased IL-6 production from lymphocytes examined ex vivo." (PMID 30836628, 2019). "IL-6 also increases the production of hepcidin, which was described to be associated with iron deficiency anaemia in mixed type of CD." (PMID 24649966, 2014). "Hepcidin is regulated by iron deficiency but also as an acute phase protein by pro-inflammatory mediators such as interleukin-6." (PMID 25646159, 2014). "Production of hepcidin is stimulated by iron overload, inflammation, and proinflammatory cytokines such as IL-6, whereas it is decreased by iron deficiency and erythropoiesis, leading to iron accumulation in the body." (PMID 18541040, 2008). "Activation of the IL-6–hepcidin axis during chronic low-grade inflammation promotes increased ferritin levels and reduced intestinal iron absorption, contributing to functional iron deficiency despite sufficient or elevated systemic iron stores." (PMID 40332421, 2025). "Incorporating inflammatory markers like CRP or interleukin-6 (IL-6) could provide a more accurate assessment of iron status by distinguishing between inflammation-induced and true iron deficiency." (PMID 40035857, 2025). "Additionally, IL-6 stimulates hepcidin production, which reduces iron absorption and restricts the release of stored iron, leading to functional iron deficiency and impaired hemoglobin synthesis." (PMID 41012833, 2025). "The intersection between psychological stress, inflammation, and iron metabolism has been recently emphasized in human studies: Psychological stress activates the HPA axis, elevates IL-6, and induces hepcidin, resulting in functional iron deficiency even with adequate intake." (PMID 41256943, 2025). "Iron deficiency could potentially influence the expression of cytokines such as IL-6, IL-1, TNF-α, and IFN-γ, contributing to tissue damage." (PMID 39161911, 2024). "Iron deficiency-induced reduction in hepcidin promotes the expression of IL6 and STAT3." (PMID 39341502, 2024). "For instance, iron deficiency is reported to blunt IL-6 responses in some settings, but not others." (PMID 39296289, 2024).
iron deficiency (continued). "In the present study, we demonstrated that iron deficiency led to an enhanced pro-inflammatory response, resulting in a marked increase in serum contents of the inflammatory cytokines, IL-1β, IL-4, IL-6, TGF-β1, and TNF-α and a trend towards increased contents of IL-12 and GM-CSF." (PMID 39296492, 2024). "Iron deficiency may also result in chronic inflammation as an effect of the action of proinflammatory cytokines (IL-6, IL1β, and IL-22), and finally increase hepcidin expression." (PMID 35160288, 2022). "In iron deficiency, the decreased function of the immune system is mediated through impaired humoral immunity, phagocytic activity, oxidative burst, and decreased interleukin-6 (IL-6) levels which can account for the increased risk of infections." (PMID 35897041, 2022). "IL-6 plays a predominant role in this process through the upregulation of hepatic hepcidin expression, which may account for the hepcidin-driven iron deficiency observed in certain autoimmune and inflammatory diseases." (PMID 33672218, 2021). "These associations suggest that iron deficiency in PwCF, as reflected by lower serum iron levels, may be a dynamic and relative state induced by IL-6 and hepcidin-25 during PEXs." (PMID 33649353, 2021). "Interestingly, IL-6 induces hepcidin, which negatively affects erythropoiesis by inducing iron deficiency, whereas cytokines such as IL-18 and IL-23 (which are produced by monocytes and/or macrophages in addition to other cells) increase IFN-γ production." (PMID 32373101, 2020). "Given the central role of hepcidin in iron metabolism, assessment of serum, urinary and hepatic hepcidin levels and inflammatory markers such as interleukins (IL-1 and IL-6) could provide insight into the aetiology of iron deficiency." (PMID 31640237, 2019). "Furthermore, a high level of Interleukin 6, a pro-inflammatory cytokine, caused by exposure to air pollution can increase hepcidin production through the signal transducer and transcription activator-3, thus inducing iron deficiency." (PMID 38594672, 2024). "However, an iron deficiency in the diet may be associated with inflammation and, at the same time, with an increase in the level of IL-6, which may affect the level of interleukins from the IL-17 family." (PMID 35277002, 2022). "Interestingly, exhaustive exercise has been shown to increase IL-6 and hepcidin levels, which may be one among several factors that cause iron deficiency in athletes following intense periods of training." (PMID 32365981, 2020). "Altogether, our data suggest that raised hepcidin levels in dialysis patients, due to several mechanisms including inflammation(IL-6)-induced synthesis and kidney retention, may contribute to a functional iron deficiency, as showed by the low serum iron and transferrin concentrations." (PMID 31296086, 2019). "However, exercise-induced acute elevation of IL-6 during daily training may cause sustained elevation of hepcidin with a concomitant increase in the risk of iron deficiency." (PMID 28335426, 2017). "The IL-6/CRP inflammatory axis stimulates hepatic hepcidin production, leading to functional iron deficiency, impaired erythropoiesis, and increased red cell anisocytosis, which raises RDW." (PMID 41231809, 2025). "In this study, iron deficiency also decreased the levels of inflammatory factors such as TNF-α, IFN-γ, IL-6 and IL-1β in the serum of neonatal pigs." (PMID 39127747, 2024). "It has been stated that iron deficiency increases HIF-1α protein expression, which upregulates the expression of IL-6 and TNFα." (PMID 37513518, 2023). "Iron deficiency at any yearly time point was associated with higher increases in hs-CRP (mean difference in change: 1.62 mg/L, 95%CI 0.98–2.26, P < .001) and IL-6 levels (mean difference in change: 1.33 ng/L, 95%CI 0.87–1.79, P < .001) over 3 years." (PMID 34533774, 2022). "Magnesium deficiency in rats causes cardiac dysfunction and inflammation, increasing the production of TNF-α, IL-1, and IL-6." (PMID 35056870, 2022).
iron deficiency (continued). "Magnesium deficiency increases the ability of macrophages to produce inflammatory cytokines, especially TNF-α, IL-1, and IL-6, resulting in the development of low-grade inflammation." (PMID 35056870, 2022). "The iron deficiency subgroup also had a significantly higher concentration of APPs (CRP and IL-6), ALP activity, and total and LDL-cholesterol levels." (PMID 34680053, 2021). "In summary, hepcidin-dependent iron deficiency in PAH is mainly due to impaired BMP signaling and the proinflammatory IL-6 axis." (PMID 33672218, 2021). "The iron deficiency subgroup has also a significantly elevated concentration of APPs (CRP and IL-6), ALP activity as well as total and LDL-cholesterol levels." (PMID 34728695, 2021). "Several studies have shown that magnesium deficiency increases the production of many pro-inflammatory cytokines (such as TNF-α, IL-6) and that this effect is accompanied by the sensitization of cells such as neutrophils, macrophages and endothelial cells." (PMID 29467509, 2018). "Recent research has shown that iron deficiency enhances mitoROS production and mitoROS-dependent NETosis, impairing the functional efficacy of neutrophils in plasma and suppressing the production of inflammatory cytokines TNF-α, IL-6, and IL-12." (PMID 39127747, 2024). "However, this scenario tends to contradict the traditional concept that IBD leads to the development of iron deficiency anemia (IDA), in which elevated levels of IL6 in IBD patients activate hepcidin expression in the liver." (PMID 39341502, 2024). "The mRNA expression of the endometrium receptivity-related genes, PR, SOX-17, CX3CR1, FKN, activin, follistatin, BMP2, as well as the examined cytokines and chemokines LIF, IL-6, and IL-1β, were significantly downregulated at DFO-induced iron deficiency in HEC-1A cells." (PMID 37175630, 2023). "Functional iron deficiency is defined by low circulating iron levels and TSAT <20% but with normal or increased serum ferritin levels (>100 μg/L) along with systemic markers of inflammation (C-reactive protein [CRP] and interleukin 6 [IL-6])." (PMID 33426933, 2021). "Ferroportin-mediated iron depletion of Hfe-/- macrophages has been demonstrated to lead to decreased production of TNF-α and interleukin (IL-6) in vitro, while altered inflammatory cytokine levels have variably been reported with HFE variants and in iron deficiency." (PMID 33057367, 2020). "Through such orchestrated control, hepcidin regulation may prevent iron deficiency from becoming severe while allowing IL-6, regardless of its levels, to exert its favorable effects on metabolism and inflammation." (PMID 41598416, 2026). "Serum IL-6 levels in patients with OSCC may be valuable markers for identifying high-risk patients and predicting treatment resistance and prognosis due to metabolic and nutritional disorders." (PMID 38510850, 2024). "In addition, patients with functional iron deficiency had significantly higher CRP, IL-6, and PCT concentrations when compared to patients with absolute iron deficiency or no iron deficiency." (PMID 34658642, 2021).
lung adenocarcinoma (106 papers, 1998 to 2026). A carcinoma that arises from the lung and is characterized by the presence of malignant glandular epithelial cells. "For example, in KRAS-mutated lung adenocarcinoma cells, the secretion of proinflammatory cytokines, including interleukin-6, activates JAK1 and JAK2 through glycoprotein 130 in an autocrine loop, thus, contributing to malignant progression." (PMID 38706597, 2024). "Dominant-negative STAT3 has been shown to reduce IL-6-induced vascular permeability associated with malignant pleural effusion in lung adenocarcinoma and decrease IgG-mediated vascular permeability during acute lung injury." (PMID 34542605, 2021). "Lung adenocarcinomas with activating mutations in EGFR was found to produce high IL-6 levels responsible for constitutive pY705-STAT3 activity." (PMID 33279931, 2020). "Systemic and pulmonary IL-6 levels are reportedly elevated in patients with lung adenocarcinoma and these elevations are associated with poor patient survival." (PMID 30931929, 2019). "IL-6, the most common and important ligand, was found to be implicated in lung adenocarcinoma in an autocrine manner." (PMID 28591704, 2017). "Collectively, the alterations in cell morphology, increased invasive capacity, acquisition of mesenchymal cell markers and loss of epithelial cell markers indicate that lung adenocarcinoma cells undergo EMT upon IL-6 stimulation." (PMID 24789104, 2014). "Altogether, TF was clearly shown to be regulated by IL-6/Stat3 signaling and involved in the formation of lung adenocarcinoma-associated MPE through modulation of vascular permeability in the tumor microenvironment." (PMID 24086497, 2013). "Possible candidates to undergo such mutations include a multitude of gene products described in studies of human lung tumors, some of these studies have implicated the EGFR/IL-6/Stat3 pathway in the pathogenesis of lung adenocarcinomas." (PMID 18461184, 2008). "However, to our knowledge, no study has evaluated the association between inflammatory markers and IL-6 levels during follow-up in patients with lung adenocarcinoma." (PMID 33167343, 2020). "Moreover, somatic-activating mutations in EGFR resulted in STAT3 over-activation through IL-6 production in human lung adenocarcinomas." (PMID 27861147, 2017). "In addition, lung adenocarcinoma patients increased both plasma concentrations of IL-2, IL-4, IL-6, and IL-10, and proportions of Latency Associated Peptide (LAP) TGF-β subset of CD4+CD25+CD127− Treg cells, which overexpressed LAP TGF-β." (PMID 26582240, 2015). "Importantly, the level of IL-6 was positively associated with the level of STAT3 phosphorylation in lung adenocarcinoma tissues when the values for each individual patient were plotted (p<0.005)." (PMID 24789104, 2014). "Finally, although several TME factors could regulate CD155 expression in tumor cells, the association between CD155 and IL-6 observed in cell lines was maintained in lung adenocarcinoma tissues and patient serum." (PMID 39596207, 2024). "In lung adenocarcinoma, IL-6 secreted by TAMs activates the JAK2/STAT3 pathway, and STAT3 can activate the expression of C/EBPβ, thereby enhancing the expression of IL-6." (PMID 40131539, 2025). "M2-like macrophages were discovered to play a substantial role in the progression of lung adenocarcinoma, and this effect was enhanced by IL-6 overexpression." (PMID 38424624, 2024). "Analyses of TCGA data to correlate prognosis with cytokine mRNA expression in lung adenocarcinoma patients identified increased levels of the mRNAs for Csf3, Cxcl1, and IL-6 as significant indicators of a worse prognosis." (PMID 39338937, 2024). "Analysis of TCGA database results revealed elevated expression of IL-6 in ever-smokers with metastasis in lung adenocarcinoma (LUAD) and lung squamous carcinoma (LUSC) patients." (PMID 38993553, 2024).